EFTUD2 (elongation factor Tu GTP binding domain containing 2)
Description:
Required for pre-mRNA splicing as component of the spliceosome, including pre-catalytic, catalytic and post-catalytic spliceosomal complexes. Component of the U5 snRNP and the U4/U6-U5 tri-snRNP complex, a building block of the spliceosome. As a component of the minor spliceosome, involved in the splicing of U12-type introns in pre-mRNAs (Probable).
Synonyms: SNRP116; U5-116KD; Snu114; SNRNP116; MFDGA; MFDM
Tractability: Small molecule: a structure with a bound ligand is known. PROTAC: UniProt records ubiquitination sites on it; ubiquitination databases record sites on it; its protein half-life has been measured.
Gene: Protein-coding gene on chromosome 17 (44,849,948 to 44,899,626, reverse strand). Ensembl gene ENSG00000108883.
Subcellular location: Nucleus
Subcellular location (Human Protein Atlas): Nucleoplasm; Cytosol; Vesicles
Pathways (Reactome):
Metabolism of RNA: mRNA Splicing - Major Pathway; mRNA Splicing - Minor Pathway
Disease: Dengue Virus-Host Interactions
Gene Ontology:
Molecular function: protein binding; RNA binding; GTPase activity; U5 snRNA binding; GTP binding
Biological process: mRNA splicing, via spliceosome; negative regulation of mRNA splicing, via spliceosome; spliceosomal snRNP assembly; spliceosomal tri-snRNP complex assembly; spliceosome conformational change to release U4 (or U4atac) and U1 (or U11); cellular response to xenobiotic stimulus; response to cocaine
Cellular component: Cajal body; catalytic step 2 spliceosome; membrane; nuclear speck; nucleoplasm; nucleus; post-mRNA release spliceosomal complex; post-spliceosomal complex; precatalytic spliceosome; spliceosomal complex; U12-type catalytic step 2 spliceosome; U12-type precatalytic spliceosome; U2-type catalytic step 1 spliceosome; U2-type catalytic step 2 spliceosome; U2-type precatalytic spliceosome; U4/U6 x U5 tri-snRNP complex; cytosol; U4atac/U6atac x U5 tri-snRNP complex; U5 snRNP
Genetic constraint (gnomAD): Loss-of-function variants: 9 observed, 108.14 expected, observed/expected ratio (o/e) 0.0832, 90% interval 0.049 to 0.14. The upper end of that interval is the gene's LOEUF score, 0.14, which puts it in group 1 of 6, group 1 being the genes least tolerant of losing a copy. Missense variants: 738 observed, 1,259.6 expected, observed/expected ratio (o/e) 0.59, 90% interval 0.55 to 0.62. Synonymous variants: 437 observed, 471.62 expected, observed/expected ratio (o/e) 0.93, 90% interval 0.86 to 1.
Gene-disease validity (ClinGen):
ClinGen rates the evidence that EFTUD2 causes each of these diseases.
mandibulofacial dysostosis-microcephaly syndrome (autosomal dominant): Definitive.
Homologues: Orthologues: chimpanzee EFTUD2 (100% identical), dog EFTUD2 (99% identical), macaque EFTUD2 (99% identical), pig EFTUD2 (99% identical), mouse Eftud2 (99% identical), rat Eftud2 (99% identical), guinea pig EFTUD2 (99% identical), tropical clawed frog eftud2 (94% identical), zebrafish eftud2 (92% identical), rabbit EFTUD2 (91% identical), Drosophila melanogaster CG4849 (75% identical), Caenorhabditis elegans eftu-2 (70% identical). Paralogues in human: EEF2 (33% identical), EFL1 (28% identical), GFM2 (16% identical), GFM1 (16% identical), GUF1 (12% identical), MTIF2 (10% identical), EEF1A1 (10% identical), HBS1L (10% identical), EEF1A2 (10% identical), GSPT1 (9% identical), EIF5B (9% identical), GSPT2 (8% identical), and 6 more.
Diseases named in the same sentence as EFTUD2 in open-access papers:
EFTUD2 is named in the same sentence as 71 diseases in open-access papers, as found by Europe PMC text mining. Sharing a sentence is not in itself a finding about the gene and the disease. The quoted sentences say what the papers report.
mandibulofacial dysostosis (23 papers, 2012 to 2026). A hereditary disorder occurring in two forms: the complete form (Franceschetti's syndrome) is characterized by antimongoloid slant of the palpebral fissures, coloboma of the lower lid, micrognathia and hypoplasia of the zygomatic arches, and microtia. "For example, variants in the splicing factor EFTUD2 that cause mandibulofacial dysostosis with microcephaly seem also to affect the splicing of MDM2." (PMID 41283296, 2025). "Heterozygous loss-of-function variants in EFTUD2 are associated with mandibulofacial dysostosis with microcephaly (MIM#610,536); however, this 23-year-old female never had microcephaly, cognitive impairment, or mandibulofacial dysostosis on examination." (PMID 40597352, 2025). "The mutations in EFTUD2 itself also lead to developmental defects and clinical manifestations in mandibulofacial dysostosis, the nervous system, the circulatory system, the digestive system and the reproductive system." (PMID 40116087, 2025). "Mutations in EFTUD2 result in mandibulofacial dysostosis indicating an increased sensitivity of craniofacial development for altered splicing efficiency." (PMID 39308865, 2024). "The genetic diagnoses in our cohort (CHARGE Syndrome, Fanconi Syndrome, EFTUD2-related mandibulofacial dysostosis) have been reported in the literature to be associated with EA/TEF." (PMID 36909054, 2023). "Mutations in EFTUD2 lead to craniofacial abnormalities, such as mandibulofacial dysostosis and esophageal atresia." (PMID 37396299, 2023). "EFTUD2 is a mRNA splicing regulator, and its mutation causes a multiple malformation syndrome termed as mandibulofacial dysostosis with microcephaly." (PMID 34257558, 2021). "Mandibulofacial dysostosis with microcephaly caused by heterozygous variants in EFTUD2 gene is characterized by the presence of progressive microcephaly, dysmorphic features and hearing loss." (PMID 34946966, 2021). "Elongation factor Tu guanosine-5’-triphosphate (GTP) binding domain containing 2 (EFTUD2) encodes a major component of the spliceosomal GTPase and, if mutated, causes mandibulofacial dysostosis with microcephaly (MFDM; MIM#610536)." (PMID 32408545, 2020). "Mutations in EFTUD2 are responsible for the autosomal dominant syndrome named MFDM (mandibulofacial dysostosis with microcephaly)." (PMID 31276534, 2019). "Similarly, EFTUD2 mutations result in mandibulofacial dysostosis with microcephaly, and mutations in PPIL1, PRP17, and PRPF19 are linked to neurodegenerative pontocerebellar hypoplasia." (PMID 40608414, 2025). "Subsequent identification of a complex EFTUD2 intragenic rearrangement confirmed an additional diagnosis of mandibulofacial dysostosis with microcephaly (MFDM)." (PMID 39243045, 2024). "Five unique genetic diagnoses including CHARGE Syndrome, Fanconi Syndrome, EFTUD2-related mandibulofacial dysostosis, and two different chromosomal deletion syndromes were made for a total of nine (13%) patients in our cohort." (PMID 36909054, 2023). "Interestingly, the first gene, VPS35 (ENSG00000069329), is associated with “Parkinson's disease (PD)”, and the second gene, EFTUD2 (ENSG00000108883), causes “mandibulofacial dysostosis with microcephaly”." (PMID 24800246, 2014). "Although this proband (SB542-1014) did show syndromic mandibulofacial anomaly and congenital cardiac defect, molecular diagnosis of the EFTUD2 variant was not made by humans, likely due to the rarity and wide spectrum of the phenotypes of mandibulofacial dysostosis, Guion–Almeida type." (PMID 34593925, 2021).
mandibulofacial dysostosis (continued). "Mandibulofacial dysostosis with microcephaly (MFDM) is a rare autosomal dominant genetic disease characterized by intellectual and growth retardations, as well as major microcephaly, induced by missense and splice site variants or microdeletions in the EFTUD2 gene." (PMID 32943010, 2020).
microcephaly (15 papers, 2012 to 2025). A congenital or acquired developmental disorder in which the circumference of the head is smaller than normal for the person's age and sex. "All patients carrying EFTUD2 mutations presented with microcephaly, hypoplasia of the zygomatic and mandibular bones, hearing loss, downslanting palpebral fissures and microtia." (PMID 40116087, 2025). "Embryonic NSC‐specific Eftud2 knockout resulted in cortical disorganization and microcephaly, while pathogenic variants led to significant neuronal loss." (PMID 40448601, 2025). "Conditional Eftud2 knockout in murine neural stem cells induces microcephaly and cortical disorganization, while pathogenic variants drive neuronal loss." (PMID 40448601, 2025). "Importantly, all patients exhibit developmental delay, 88% of them have microcephaly, and all carry a mutation in EFTUD2." (PMID 31276534, 2019). "We identified a novel frameshift variant of EFTUD2 (c.1030_1031delTG, p.Trp344fs*2) in an MFDM Chinese patient with craniofacial dysmorphism including ear canal structures and microcephaly, mild intellectual disability, and developmental delay." (PMID 31806011, 2019). "Another mutation, c.2624dupT (p.Ile875fs), was linked to Guion-Almeida type mandibulofacial dysostosis with microcephaly (MFDM), resulting in a truncated EFTUD2 protein." (PMID 40116087, 2025).
hepatocellular carcinoma (8 papers, 2020 to 2025). A malignant tumor that arises from hepatocytes. "Recent research has revealed that elevated EFTUD2 expression in hepatocellular carcinomas is closely linked to tumor growth and poor survival." (PMID 40650074, 2025). "This association is substantiated by the observation that EFTUD2 sustains cancer cell viability and enhances the progression of hepatocellular carcinoma through STAT3 activation." (PMID 40650074, 2025). "This association is substantiated by observation that EFTUD2 sustains cancer cell viability and enhances the progression of hepatocellular carcinoma through STAT3 activation." (PMID 38163859, 2024). "High expression of EFTUD2 in hepatocellular carcinoma patients is associated with clinical features and is pivotal in hepatocellular carcinoma cell proliferation and cell cycle course." (PMID 35126467, 2021). "Furthermore, the overexpression of EFTUD2 promotes the progression of hepatocellular carcinoma, breast cancer and colorectal cancer." (PMID 40116087, 2025). "Furthermore, research in hepatocellular carcinoma has revealed a connection between EFTUD2 and metabolic reprogramming, where EFTUD2 regulates the protein stability of YTHDF3, an m6A “reader” protein involved in RNA metabolism." (PMID 40650074, 2025). "EFTUD2 is markedly overexpressed in hepatocellular carcinoma tissues." (PMID 35126467, 2021). "Notably, we detected high expression of wild-type EFTUD2 in this patient, consistent with its reported oncogenic role in hepatocellular carcinoma, and suggesting that EFTUD2 may also contribute to leukemogenesis in ALL." (PMID 41333018, 2025). "EFTUD2 has been noted to increase hepatocellular carcinoma (HCC) cell survival and metastasis by inducing epithelial–mesenchymal transition and be associated with immune infiltration and poor prognosis, making it a potential therapeutic target for liver cancer." (PMID 40236649, 2025). "These analyses suggest that EFTUD2, GAPDH, NOP56, and PA2G4 were potential biomarkers for the diagnosis and prognosis of hepatocellular carcinoma." (PMID 34257558, 2021). "However, the role of EFTUD2 in solid tumors, including hepatocellular carcinoma (HCC), remains unexplored." (PMID 33024090, 2020).
viral infection (8 papers, 2016 to 2025). "Notably, this regulatory effect was only observed under NDV infection conditions, suggesting EFTUD2 modulates chMDA5 splicing in association with viral infection." (PMID 40580566, 2025). "Further research with HCV showed that EFTUD2 contributes to the antiviral response through RIG-I/MDA5 pre-mRNA maturation and it was found that viral infection down-regulates EFTUD2, resulting in splicing alteration of antiviral factors." (PMID 27575636, 2016). "In this study, we systemically deciphered the impact of the viral μ2 protein from MRV on transcripts encoding the U5 snRNP proteins EFTUD2, PRPF8, and SNRNP200, in an effort to understand how μ2 triggers a reduction in the level of their corresponding proteins during viral infection." (PMID 36614170, 2022). "Notably, ectopic expression of the μ2 protein is not able to induce any reduction of EFTUD2, whereas during viral infection, a significant reduction of EFTUD2 protein level (close to 25%) was previously shown." (PMID 36614170, 2022). "Study has shown that EFTUD2 plays an important role in innate immune response to virus infection." (PMID 34257558, 2021). "For example, cytoplasmic EFTUD2 and SNRNP200 act as RNA sensors that induce interferon production during viral infection." (PMID 40580566, 2025). "For instance, we demonstrated that EFTUD2 and SNRNP200 are required for both apoptosis and necroptosis, whereas EFTUD2 and PRPF8 are required for optimal interferon response against viral infection." (PMID 36560714, 2022). "The results presented herein highlight novel roles of U5 snRNP proteins EFTUD2, PRPF8, and SNRNP200 in apoptosis, necroptosis, and interferon induction, using MRV as a model for viral infection." (PMID 36560714, 2022). "We demonstrated that EFTUD2 and SNRNP200 are required for both apoptosis and necroptosis, whereas EFTUD2 and PRPF8 are required for optimal interferon response against viral infection." (PMID 36560714, 2022). "In this study, we demonstrated distinct and overlapping crucial roles of U5 snRNP core components EFTUD2, PRPF8, and SNRNP200 on apoptosis, necroptosis, and interferon induction during viral infection, using MRV as a model virus." (PMID 36560714, 2022). "Indeed, both EFTUD2 and SNRNP200 have been shown to act as RNA sensors in the cytoplasm to allow the induction of the IFN response pathway during viral infection." (PMID 35489070, 2022). "In the present study, we deciphered the impact of EFTUD2, PRPF8, and SNRNP200 silencing on viral replication using MRV as a model and discovered novel roles for EFTUD2 and SNRNP200 in cell survival, apoptosis, and necroptosis during viral infection." (PMID 36560714, 2022).
breast carcinoma (5 papers, 2015 to 2025). "Deletion of EFTUD2 inhibits the association of endogenous proteins, leading to increased apoptosis in breast cancer cells." (PMID 33024090, 2020). "In this report, we demonstrate that depletion of SNW1 and its associating factor, EFTUD2, induced apoptosis in breast cancer cells." (PMID 25450007, 2015). "Meanwhile, it has been reported that direct interaction between SNW1 and EFTUD2 is essential for cell survival in breast cancer." (PMID 33024090, 2020). "It is proved that depletion of SNW domain containing 1 (SNW1) and its related factor EFTUD2 can induce breast cancer cell apoptosis." (PMID 32537629, 2020). "In this report, we demonstrate that SNW1 directly associates with EFTUD2 and SNRNP200 and that disruption of SNW1 association with these proteins promotes the apoptosis of breast cancer cells." (PMID 25450007, 2015). "A study reported that EFTUD2 expression is markedly elevated in breast cancer cells." (PMID 40116087, 2025). "Thus, the interaction between EFTUD2 and SNW1 is crucial for the survival of breast cancer cells, because its disruption will lead to increased apoptosis." (PMID 40116087, 2025).
Guion-Almeida type mandibulofacial dysostosis (5 papers, 2013 to 2025). "Elongation Factor Tu GTP‐Binding Domain Containing 2 (EFTUD2), a core spliceosomal GTPase associated with Mandibulofacial Dysostosis with Microcephaly (MFDM), plays a mechanistically undefined role in cerebral development." (PMID 40448601, 2025). "The craniofacial disorder mandibulofacial dysostosis Guion-Almeida type is caused by haploinsufficiency of the U5 snRNP gene EFTUD2/SNU114." (PMID 31304552, 2019). "Mutations in EFTUD2 were proven to cause a very distinct mandibulofacial dysostosis type Guion-Almeida (MFDGA, OMIM #610536)." (PMID 23879989, 2013). "In 2012, the EFTUD2 gene was found to cause a very distinct condition with phenotypic overlap with Treacher Collins syndrome, the mandibulofacial dysostosis type Guion-Almeida (MFDGA)." (PMID 23879989, 2013).
colorectal cancer (4 papers, 2023 to 2025). A primary or metastatic malignant neoplasm that affects the colon or rectum. "Our research began by identifying a significant upregulation of EFTUD2 in 5-FU-resistant colorectal cancer tissues, and subsequent Gene Set Enrichment Analysis (GSEA) indicated its association with chemotherapy-resistant phenotypes." (PMID 38163859, 2024). "EFTUD2 is known to be a modulator of the innate immune system: in colorectal cancer, EFTUD2 seems to promote tumor growth, especially in a colitis-associated environment and by modulation of macrophages." (PMID 36068443, 2023). "This hypothesis is supported by studies in other cancers, such as colorectal cancer, where EFTUD2 has been shown to influence c-MYC stability and contribute to chemoresistance." (PMID 40650074, 2025). "Therefore, further investigation into the inflammatory characteristics of EFTUD2 in colorectal cancer progression is crucial for improving treatment and prognosis." (PMID 40116087, 2025). "Whether EFTUD2 contributes to colorectal cancer progression by enhancing this inflammatory response remains to be investigated." (PMID 40116087, 2025).
endometrial cancer (4 papers, 2023 to 2025). Primary or metastatic malignant neoplasm involving the endometrium (mucous membrane that lines the endometrial cavity). "Consistent with those for HCC and endometrial cancer, our results also demonstrated that EFTUD2 not only functions as a poor prognosis indicator but also has a substantial diagnostic value in LUAD." (PMID 40236649, 2025). "For example, in endometrial cancer, EFTUD2 expression correlated with poor prognosis and was linked to increased expression of RIG-I, suggesting an interplay between EFTUD2 and the tumor microenvironment." (PMID 40650074, 2025). "In addition, a clinical study has shown that high expression of EFTUD2 in endometrial cancer is predictive of poor prognosis." (PMID 40116087, 2025). "The aim of this study was to examine the expression of RIG-I and EFTUD2 in endometrial cancer." (PMID 36068443, 2023). "For endometrial cancer, an immunogenic cancer, data about RIG-I and EFTUD2 are still missing." (PMID 36068443, 2023). "In multivariate Cox regression analysis, EFTUD2 was identified as an independent marker for progression-free survival in endometrial cancer and could serve as a negative prognostic indicator for patients." (PMID 40116087, 2025).
Esophageal atresia (4 papers, 2013 to 2025). A developmental defect resulting in complete obliteration of the lumen of the esophagus such that the esophagus ends in a blind pouch rather than connecting to the stomach. "A heterozygous 5-bp deletion in IVS 12 (c.1058 + 3_1058 + 7del) of EFTUD2 was initially reported as a causal variant in a subject with craniofacial anomaly, esophageal atresia, congenital cardiac defect, and microtia." (PMID 32408545, 2020). "In addition to AFD type Guion-Almeida and syndromic esophageal atresia, oto-facial syndrome also belongs to the EFTUD2 mutation spectrum." (PMID 23879989, 2013). "Recently, gross deletions and mutations in EFTUD2 were determined to cause syndromic esophageal atresia (EA), as well." (PMID 23879989, 2013).
Intellectual disability (4 papers, 2013 to 2025). "In a study involving 12 patients with congenital anomalies and/or intellectual disabilities and their trios, researchers identified two EFTUD2 mutations through whole-exome sequencing." (PMID 40116087, 2025). "Various signs indicate that EFTUD2 mutations are probably an important factor in brain abnormalities, such as intellectual disabilities or epilepsy caused by developmental defects." (PMID 40116087, 2025). "However, the specific targets and mechanisms through which EFTUD2 is involved in intellectual disabilities have not been clarified and thus require further investigation." (PMID 40116087, 2025).